TFRC (transferrin receptor)
Diseases named in the same sentence as TFRC in open-access papers (continued):
Sharing a sentence is not in itself a finding about the gene and the disease.
head and neck squamous cell carcinoma (4 papers, 2020 to 2025). A squamous cell carcinoma that arises from any of the following anatomic sites: lip and oral cavity, nasal cavity, paranasal sinuses, pharynx, larynx, and salivary glands. "It has been shown that in head and neck squamous cell carcinomas (HNSCCs), the YTH structural domain of the m6A reader YTHDF1 interacts with the 3′UTR and 5′UTR of TFRC mRNA." (PMID 38550378, 2024). "In head and neck squamous cell carcinoma, YTHDF1 regulates iron metabolism by methylating TFRC (m6A methylation)." (PMID 37088822, 2023).
Hyperglycemia (4 papers, 2014 to 2025). An increased concentration of glucose in the blood. "The balance between O2•- and •OH in T2DM is modulated by three critical factors: First, T2DM disease duration: Long-term hyperglycemia (≥10 years) promotes iron accumulation in skeletal muscle via upregulating transferrin receptor 1, increasing •OH production by enhancing Fenton reactions." (PMID 41195385, 2025). "Under hyperglycemia combined with hypoxia up to 12 hr, the expression of RPLP0, TFRC, GUSB, and ACTB genes remained unchanged." (PMID 25193495, 2014). "Under hyperglycemia combined with hypoxia, gene expression of GUSB, TFRC, RPLP0, and ACTB turned out to be stable in all time intervals measured (1, 3, and 12 hr)." (PMID 25193495, 2014). "Our findings strongly confirm that RPLP0 and TFRC are the most suitable reference genes for HUVEC gene expression experiments subjected to hypoxia and/or hyperglycemia for the given experimental conditions." (PMID 25193495, 2014). "Therefore, this is the first report indicating TFRC and RPLP0 as suitable reference genes in HUVEC exposed to hypoxia, hyperglycemia, or hypoxia and hyperglycemia combined." (PMID 25193495, 2014). "In contrast, we applied shorter incubation times (1, 3, and 12 hr) and identified two reference genes, namely RPLP0 and TFRC, as the most stably expressed under both euglycemia and hyperglycemia, in the presence or absence of hypoxia." (PMID 25193495, 2014).
injury (4 papers, 2017 to 2025). Damage inflicted on the body as the direct or indirect result of an external force, with or without disruption of structural continuity. "At the same time, changes in iron-metabolism-related proteins also affect the process of ferroptosis, such as the increased expression of transferrin receptor 1 (TfR1), which is associated with ferroptosis after traumatic brain injury." (PMID 40143112, 2025). "Transferrin is generated in the liver as the major serum iron-binding protein in the body, and both transferrin and the transferrin receptor were found to change expression during chemically induced liver injury." (PMID 28115551, 2017).
mental disorder (4 papers, 2019 to 2022). A disease that has its basis in the disruption of mental process. "The expression level of TFRC is associated with mental disorders, suggesting that TERC could use as a molecular target for studying the pathogenesis of DEP." (PMID 32457667, 2020). "Some studies have found that the expression level of TFRC is associated with mental disorders, suggesting that TFRC may be useful as a molecular target for studying the pathogenesis of DEP." (PMID 32457667, 2020). "In addition, another study found that TFRC expression levels are associated with mental disorders, suggesting that we can use TFRC as the molecular target for the study of the occurrence and development mechanism of DD33." (PMID 31341180, 2019). "Although the patient's deletion is relatively small, it partly overlaps the canonical 3q29 deletion (defined between TFRC and DLG1 gene) and extends upstream, associating a different facial phenotype compared to the classic 3q29 deletion, nonetheless showing a similar psychiatric disorder." (PMID 31338352, 2019).
metastatic disease (4 papers, 2015 to 2025). "Within metastatic tumors, pH-CT sensed the peripheral dysregulated pH through allosteric i-motif, enforcing the dynamic reassembly of two subcomponents and facilitating heterodimerization of c-Met and transferrin receptor (TfR)." (PMID 40041032, 2025).
periodontitis (4 papers, 2022 to 2025). An acute or chronic inflammatory process that affects the tissues that surround and support the teeth. "TFRC was remarkably upregulated in periodontitis ligament tissues of periodontitis patients and LPS-PG treated PDLSCs." (PMID 35611986, 2022). "In this research, TFRC was confirmed to be a target gene of miR-370 and upregulated in periodontitis model cells." (PMID 35611986, 2022). "Additionally, LINC00616 not only downregulates the expression of GPX4 and SLC7A11 but also targets miR-370, indirectly influencing and enhancing the levels of TFRC, thereby promoting the occurrence of ferroptosis, LINC00616 knockdown may be a promising therapeutic strategy for periodontitis." (PMID 40454168, 2025).
polycystic ovary syndrome (4 papers, 2022 to 2023). A disorder that manifests as multiple cysts on the ovaries. "In a mouse model of DHEA-induced polycystic ovary syndrome, iron salts were found to stimulate TFRC, increase iron levels, and trigger various forms of programmed cell death." (PMID 37299424, 2023). "In the dehydroepiandrosterone-induced mouse model of polycystic ovary syndrome, ferric salt stimulated TFRC which augmented the Fe content, brought about ROS liberation, stimulated mitophagy, and triggered lipid peroxidation, further promoting the ferroptosis of KGN human granulosa-like tumor cells." (PMID 36293552, 2022). "In patients with polycystic ovary syndrome (PCOS), iron-mediated mitophagy has been found to promote ferroptosis by activating TFRC/PINK1 signaling." (PMID 36198708, 2022).
renal fibrosis (4 papers, 2022 to 2025). A final common manifestation of a wide variety of chronic kidney diseases characterized by glomerulosclerosis and tubulointerstitial fibrosis. "Supporting a role for TFRC in renal fibrosis are studies in which mice heterozygous for the Tfrc gene show reduced renal fibrosis in the UUO and DN models." (PMID 38625739, 2024). "Some researchers have also demonstrated that TFRC-deleted mice exhibit attenuated renal fibrosis, along with reduced renal expression of ferritin and 4-hydroxynonenal, compared with WT mice." (PMID 35821227, 2022). "TFRC, on the other hand, enables TGF-β-induced craniofacial morphogenesis and TGF-β-induced renal fibrosis." (PMID 37887338, 2023).
sarcoma (4 papers, 2022 to 2025). A usually aggressive malignant neoplasm of the soft tissue or bone. "To clarify the association between iron metabolism and the prognosis of sarcoma in clinical practice, we investigated the relationship between OS and the expression levels of the TFRC, FPN, and FTH1 genes in patient samples." (PMID 37444594, 2023). "A similar finding was obtained when analyzing data for synovial sarcoma patients treated in our institute, although the sample number was too small to reach a definitive conclusion about the role of TFRC in sarcoma." (PMID 37444594, 2023). "Our initial experiment showed that TFRC was expressed at a high level in most sarcoma cell lines examined." (PMID 37444594, 2023). "Our findings suggest that ferroptosis could have a therapeutic effect in sarcoma, particularly in subpopulations with high TFRC and SHARPIN expression." (PMID 37444594, 2023). "In summary, we suggest that ferroptosis could be a therapeutic target in sarcoma, particularly in subpopulations with high TFRC and SHARPIN expression." (PMID 37444594, 2023). "Overall, our findings suggest that ferroptosis may be a promising therapeutic target in sarcoma, particularly in subpopulations with poor prognosis due to high TFRC and SHARPIN expression." (PMID 37444594, 2023). "Based on the results presented above, we propose that sarcoma is characterized by increased expression of TFRC and SHARPIN, with high GPX4 dependency, suggesting that ferroptosis may be a promising therapeutic target for sarcoma." (PMID 37444594, 2023). "In line with the qPCR data, an immunoblot analysis revealed that TFRC protein expression was higher in the KAS, NEPS, U2OS, 143B, Aska, Yamato, and HT1080 sarcoma cell lines than in HDF, 293T cells, and HeLa cells." (PMID 37444594, 2023). "Accordingly, it has been shown that the transferrin receptor 1 (TfR1) and the epidermal growth factor receptors 1 and 2 (EGFR1, Her2) are overexpressed in early and advanced sarcoma, thus representing potential targets of interest in IT-based sarcoma therapy." (PMID 40559886, 2025). "In addition, by using the GEPIA online data analysis platform, we found that in the sarcoma dataset (SARC, n=262), patients with high TFRC gene expression had significantly shorter overall survival than did those with low TFRC gene expression (P=0.035)." (PMID 40510157, 2025). "In addition to TFRC, SHARPIN mRNA expression was also higher in various sarcoma cell lines, except VAESBJ, SW872 and HT1080." (PMID 37444594, 2023). "We found that TFRC, an iron uptake protein, was expressed at higher levels in sarcoma cell lines than in noncancer and carcinoma cell lines." (PMID 37444594, 2023). "First, we used quantitative PCR (qPCR) to compare the expression levels of the TFRC mRNA in noncancer, carcinoma, and sarcoma cell lines." (PMID 37444594, 2023). "TFRC mRNA was more abundant in most sarcoma cell lines than in noncancer or carcinoma cell lines." (PMID 37444594, 2023). "In addition, TFRC and SHARPIN were expressed at higher levels in sarcoma cell lines than in noncancer and carcinoma cell lines." (PMID 37444594, 2023).
steatosis (4 papers, 2015 to 2025). Increased lipid within the cytoplasm of cells. "These include the transferrin receptor (Tfrc), indicating crosstalk between iron and lipid metabolism, and Serpine1, implicated in fibrosis, suggesting that fibrogenesis is regulated by both steatosis and iron." (PMID 31510077, 2019).
T-cell acute lymphoblastic leukemia (4 papers, 2008 to 2024). Acute lymphoblastic leukemia of T-cell origin. "Only a few genes, such as HES4, HEY1, MYC, NOTCH3, NRARP, and TFRC, are similarly regulated in mutationally activated NOTCH1-driven cancers, such as T-cell acute lymphoblastic leukemia (T-ALL), mantle cell lymphoma (MCL), and breast cancer." (PMID 33003595, 2020).
acute leukemia (3 papers, 2021 to 2024). A clonal (malignant) hematopoietic disorder with an acute onset, affecting the bone marrow and the peripheral blood. "CD71 (transferrin receptor 1, TfR-1) has also been utilized as a marker in diagnosing acute leukemia." (PMID 39194693, 2024).
amyotrophic lateral sclerosis (3 papers, 2018 to 2025). Amyotrophic lateral sclerosis (ALS) is a neurodegenerative disease characterized by progressive muscular paralysis reflecting degeneration of motor neurons in the primary motor cortex, corticospinal tracts, brainstem and spinal cord. "In amyotrophic lateral sclerosis (ALS), elevated ferritin and transferrin receptor levels in cerebrospinal fluid have been associated with reduced survival, suggesting that disrupted iron metabolism may serve as both a biomarker and a therapeutic target." (PMID 40951640, 2025).
Anaplastic Thyroid Carcinoma (3 papers, 2014 to 2023). "Several reports have shown that certain human tumors, such as anaplastic thyroid cancer and astrocytic brain tumors, have abnormal TFRC overexpression." (PMID 34868339, 2021).
beta thalassemia (3 papers, 2003 to 2024). Beta-thalassemia (BT) is characterized by deficiency (Beta+) or absence (Beta0) of synthesis of the beta globin chains of hemoglobin (Hb). "Despite the same pre-transfusion haemoglobin concentration, male patients with transfusion-dependent beta-thalassaemia have higher erythropoiesis (eg, soluble transferrin receptor and reticulocyte concentrations) than female patients." (PMID 38432242, 2024).
brain injury (3 papers, 2021 to 2024). Acute and chronic (see also brain INJURIES, CHRONIC) injuries to the brain, including the cerebral hemispheres, CEREBELLUM, and brain STEM. "This suggests that the iron transport proteins TFRC is aberrantly induced after ischemic brain injury and contributes to toxic iron accumulation through multiple mechanisms, representing potential therapeutic targets." (PMID 38302612, 2024).
Cirrhosis (3 papers, 2016 to 2026). A chronic disorder of the liver in which liver tissue becomes scarred and is partially replaced by regenerative nodules and fibrotic tissue resulting in loss of liver function. "However, unlike NCPF, cirrhosis exhibited decreased CD71+ transferrin receptor (TfR1) expression over erythroid cells and increased immature erythrocytes (p < 0.05) in peripheral circulation." (PMID 42193114, 2026).
colorectal adenocarcinoma (3 papers, 2013 to 2025). The most common type of colorectal carcinoma. "Moreover, in colorectal adenocarcinoma, miR-107 overexpression has been strongly associated with the regulation of specific target genes that influence tumor progression, such as transferrin receptor 1 (TFR1)." (PMID 41226545, 2025). "Using TCGA colorectal adenocarcinoma Firehose legacy dataset from cBioPortal platform, we found that the TFRC protein expression was positively correlated with the CTNNB1 protein expression, whereas the CTNNB1 protein expression was negatively correlated with APC mRNA expression." (PMID 36703617, 2023).
fibrosarcoma (3 papers, 2020 to 2023). A malignant mesenchymal fibroblastic neoplasm affecting the soft tissue and bone. "Regarding the effects of aqueous extracts of A. muricata on HT-1080 fibrosarcoma cell iron metabolism, validation studies revealed an increase in transferrin receptor TFR1 and a decrease in the intracellular levels of ferritin." (PMID 37569395, 2023). "In human fibrosarcoma cells, TFRC is a specific ferroptosis marker." (PMID 35372510, 2022).
keloid (3 papers, 2024 to 2025). An irregularly shaped, elevated mark on the skin caused by deposits of excessive amounts of collagen during wound healing. "Then, our RT-qPCR analysis implicated that SLC7A11 (P < 0.001), GPX4 (P < 0.001), and Nrf2 mRNA (P < 0.001) levels were decreased and TFRC mRNA level was increased in keloid tissues." (PMID 38887622, 2024). "Our results implicated that SLC7A11, GPX4, and Nrf2 were remarkably downregulated and TFRC upregulated in keloid tissues." (PMID 38887622, 2024). "Furthermore, SLC7A11 (P < 0.001), GPX4 (P < 0.001), and Nrf2 (P < 0.001) protein levels were significantly downregulated and TFRC protein level was (P < 0.001) upregulated in keloid tissues." (PMID 38887622, 2024). "SLC7A11, GPX4, and Nrf2 were downregulated and TFRC was upregulated in keloid tissues and KFs." (PMID 38887622, 2024). "SLC7A11, GPX4, and Nrf2 were significantly downregulated and TFRC upregulated in keloid tissues." (PMID 38887622, 2024). "Additionally, iron has been demonstrated to accumulate in keloid tissue, along with significant downregulation of SLC7A11, GPX4, and Nrf2 and upregulation of transferrin receptor protein 1 (TFRC)." (PMID 39958433, 2025). "To explore whether ferroptosis is involved in keloid development, we collected keloid tissues (n = 70) from keloid patients and normal skin tissues from healthy controls (n = 40), and iron content and SLC7A11, GPX4, Nrf2 and TFRC levels were determined." (PMID 38887622, 2024).
meningioma (3 papers, 2009 to 2023). A generally slow growing tumor attached to the dura mater. "According to the published reports, transferrin receptor 1 showed a higher expression in high grade tumor tissues of meningioma and different cancers." (PMID 37770851, 2023).
osteoarthritis (3 papers, 2023 to 2025). A noninflammatory degenerative joint disease occurring chiefly in older persons, characterized by degeneration of the articular cartilage, hypertrophy of bone at the margins and changes in the synovial membrane. "We also firstly identified that TFRC was upregulated in osteoarthritis, and could sensitize cells to ferroptosis, which might serve as a potential target for OA treatment in the future." (PMID 36950524, 2023). "And to our knowledge, the relationship between OA and TFRC was not reported before; so we firstly identified that TFRC was upregulated in IL-1β-stimulating chondrocytes, simulating the pathophysiological state of patients with osteoarthritis." (PMID 36950524, 2023).
osteoporosis (3 papers, 2023 to 2025). A condition of reduced bone mass, with decreased cortical thickness and a decrease in the number and size of the trabeculae of cancellous bone (but normal chemical composition), resulting in increased fracture incidence. "It is worth noting that in the analysis of differential genes, we found that the standard proteins of ferroptosis TFRC were significantly regulated after Rhizome Drynaria intervention, so we can speculate that ferroptosis also plays an important role in osteoporosis." (PMID 38099525, 2024).
renal carcinoma (3 papers, 2021 to 2025). A carcinoma arising from the epithelium of the renal parenchyma or the renal pelvis. "IREB2 stabilizes the mRNA of TFRC and DMT1 that code for iron transporters, leading to increased intracellular iron concentration 63 and is dysregulated in lung 64 and renal cancers." (PMID 40083931, 2025). "The results of the Kaplan–Meier test showed that the levels of TFRC and SQLE expression were not related to the survival of patients with renal cancer." (PMID 35360452, 2021).
tauopathy (3 papers, 2021 to 2023). Neurodegenerative disorders involving deposition of abnormal tau protein isoforms (tau proteins) in neurons and glial cells in the brain. "The TfR aptamer selectively targets the transferrin receptor on the BBB, while the tau aptamer binds to the tau protein and disrupts the tauopathy process in the brain." (PMID 37511539, 2023).
acute respiratory distress syndrome (2 papers, 2024 to 2025). Progressive and life-threatening pulmonary distress in the absence of an underlying pulmonary condition, usually following major trauma or surgery. "For instance, upregulation of transferrin receptor protein 1 has been observed in animal models of inflammation and in patients with acute respiratory distress syndrome." (PMID 39189262, 2024).
atrial fibrillation (2 papers, 2025 to 2026). A disorder characterized by an electrocardiographic finding of a supraventricular arrhythmia characterized by the replacement of consistent P waves by rapid oscillations or fibrillatory waves that vary in size, shape and timing and are accompanied by an irregular ventricular response. "In in vitro and in vivo preclinical models, knocking down transferrin receptor reduced atrial fibrillation by limiting ferroptosis and atrial fibrosis, directly linking CD71/iron pathways to arrhythmia." (PMID 41375568, 2025).
Burkitt lymphoma (2 papers, 2019 to 2023). A rare form of malignant mature B-cell non-Hodgkin lymphoma. "At high but nontoxic concentrations of each antibiotic, only chloramphenicol treatment of the Burkitt’s lymphoma cell line CA46 showed enhanced cytotoxicity when paired with an anti-transferrin receptor/PE RIT." (PMID 31133049, 2019).
cardiac ischemia (2 papers, 2010 to 2025). "MiR-320 regulates cardiac ischemia/reperfusion injury and cell proliferation by targeting heat-shock protein 20 and transferrin receptor 1, respectively." (PMID 20806079, 2010).
cerebral infarction (2 papers, 2024 to 2025). An ischemic condition of the brain, producing a persistent focal neurological deficit in the area of distribution of the cerebral arteries. "Researchers have developed a transferrin receptor (TfR)-targeted nanocarrier (PATRC) aimed at enhancing penetration of the blood-brain barrier (BBB) for cerebral infarction treatment." (PMID 39502285, 2024).
E. coli infection (2 papers, 2021 to 2023). "Further qRT-PCR assays showed that representative genes of phagosome maturation were significantly upregulated in response to E. coli infection including ATP6V1A, ATP6V1B2, BF2, CTSS, and TFRC, while COLEC12 was downregulated at 72 h." (PMID 36411420, 2023).